CPSF4 (cleavage and polyadenylation specific factor 4)
Description:
Component of the cleavage and polyadenylation specificity factor (CPSF) complex that play a key role in pre-mRNA 3'-end formation, recognizing the AAUAAA signal sequence and interacting with poly(A) polymerase and other factors to bring about cleavage and poly(A) addition. CPSF4 binds RNA polymers with a preference for poly(U).
Synonyms: Neb-1; CPSF30; NAR; NEB1
Tractability: PROTAC: ubiquitination databases record sites on it; its protein half-life has been measured.
Gene: Protein-coding gene on chromosome 7 (99,438,908 to 99,457,377, forward strand). Ensembl gene ENSG00000160917.
Subcellular location: Nucleus
Subcellular location (Human Protein Atlas): Nucleoplasm; Vesicles
Pathways (Reactome):
Metabolism of RNA: Processing of Intronless Pre-mRNAs; Transport of Mature mRNA Derived from an Intronless Transcript; mRNA 3'-end processing; mRNA Polyadenylation; tRNA processing in the nucleus
Disease: Dengue Virus-Host Interactions; Inhibition of Host mRNA Processing and RNA Silencing
Gene expression (Transcription): RNA Polymerase II Transcription Termination
Gene Ontology:
Molecular function: protein binding; RNA binding; sequence-specific double-stranded DNA binding; metal ion binding; nucleic acid binding; zinc ion binding
Biological process: mRNA 3'-end processing
Cellular component: mRNA cleavage and polyadenylation specificity factor complex; nucleoplasm; nucleus
Genetic constraint (gnomAD): Loss-of-function variants: 11 observed, 37.94 expected, observed/expected ratio (o/e) 0.29, 90% interval 0.18 to 0.48. The upper end of that interval is the gene's LOEUF score, 0.48, which puts it in group 2 of 6, group 1 being the genes least tolerant of losing a copy. Missense variants: 144 observed, 366.29 expected, observed/expected ratio (o/e) 0.39, 90% interval 0.34 to 0.45. Synonymous variants: 132 observed, 139.46 expected, observed/expected ratio (o/e) 0.95, 90% interval 0.82 to 1.09.
Homologues: Orthologues: chimpanzee CPSF4 (99% identical), mouse Cpsf4 (99% identical), rat Cpsf4 (99% identical), dog CPSF4 (99% identical), rabbit CPSF4 (99% identical), tropical clawed frog cpsf4 (91% identical), guinea pig CPSF4 (90% identical), rat Cpsf4l2 (88% identical), zebrafish cpsf4 (86% identical), pig CPSF4 (78% identical), macaque CPSF4 (74% identical), Drosophila melanogaster Clp (58% identical), and 1 more. Paralogues in human: CPSF4L (42% identical), ZC3H3 (28% identical).
Diseases named in the same sentence as CPSF4 in open-access papers:
CPSF4 is named in the same sentence as 25 diseases in open-access papers, as found by Europe PMC text mining. Sharing a sentence is not in itself a finding about the gene and the disease. The quoted sentences say what the papers report.
lung carcinoma (6 papers, 2013 to 2023). "In this study, we investigated the biological role and clinical significance of CPSF4 in lung cancer growth and survival and elucidated its underlying molecular mechanisms." (PMID 24358221, 2013). "To identify the underlying molecular mechanisms by which CPSF4 ovexexpression increased lung cancer cell growth, we analyzed the effect of CPSF4 on the activation of AKT and MAPK signaling by Western blot." (PMID 24358221, 2013). "Knockdown of CPSF4 can inhibit the proliferation, migration, and invasion of lung cancer cells in vitro, as well as the tumor growth in mice." (PMID 36349192, 2022). "As an important component of APA, CPSF is usually upregulated in cancers, such as CPSF1 in HCC and ovarian cancer, CPSF3 in HCC, CPSF4 in colorectal and lung cancers, and CPSF7 in HCC." (PMID 36349192, 2022). "For example, the knockdown of CPSF4 inhibits the proliferation, migration, and invasion of colorectal and lung cancer cells." (PMID 36349192, 2022). "Suppression of CPSF4 by siRNA inhibited lung cancer cells proliferation, colony formation, and induced apoptosis." (PMID 24358221, 2013). "Knockdown of CPSF4 in lung cancers leads to reduced cell growth, proliferation and increased apoptosis in lung adenocarcinoma cell lines with high endogenous levels of CPSF4." (PMID 24358221, 2013). "In this study, we observed that siRNA-mediated CPSF4 knockdown inhibited cell growth and induced apoptosis in lung cancer cells expressing high levels of CPSF4." (PMID 24358221, 2013). "To identify the potential molecular mechanisms by which CPSF4 knockdown inhibited lung cancer cell survival and proliferation, we analyzed the activities of several pro-survival proteins by Western blot analysis." (PMID 24358221, 2013). "Although further detailed analyses are necessary to determine the direct targets of CPSF4, the findings in this study imply the biological importance of CPSF4 in regulating lung cancer cell growth and survival." (PMID 24358221, 2013). "In summary, CPSF4 was highly expressed in lung cancer cell lines and tumor tissues and positively correlated with poor prognosis of patients with lung adenocarcinomas." (PMID 24358221, 2013). "Collectively, these results demonstrate that CPSF4 plays a critical role in regulating lung cancer cell proliferation and survival and may be a potential prognostic biomarker and therapeutic target for lung adenocarcinoma." (PMID 24358221, 2013). "It is still unknown why CPSF4 was overexpressed in lung cancer cells; however, based on the findings in the present study, we believe that CPSF4 may be a potential diagnostic and/or therapeutic target in lung adenocarcinomas." (PMID 24358221, 2013). "All of these findings suggest that CPSF4 may have an important role in promoting more aggressive behavior of lung cancer cells." (PMID 24358221, 2013). "Thus, our results provide a rationale for pharmacologic investigation of CPSF4 as a potential novel therapeutic target in lung cancer." (PMID 24358221, 2013). "Inactivation of PI3K/AKT, MAPK signaling pathways by CPSF4 knockdown, as indicated by suppressed the phosphorylation of PI3K, AKT, ERK1/2 and JNK, was observed in lung cancer cell lines." (PMID 24358221, 2013). "CPSF4-positive staining was observed in the nucleus of lung cancer cells, but staining was negative in adjacent non-malignant lung tissues." (PMID 24358221, 2013). "Thus, CPSF4 might exert its growth-regulating effect, at least in part, by modulating the PI3K/AKT and MAPK signaling pathways in lung cancer cells." (PMID 24358221, 2013). "A positive staining of CPSF4 was observed in the nucleus of lung cancer cells, whereas CPSF4 staining could not be detected in all 8 normal tissues, suggesting that CPSF4 might be a potential biomarker for lung adenocarcinomas." (PMID 24358221, 2013).
breast carcinoma (5 papers, 2021 to 2025). "For example, miR-4458 expression was reduced in breast cancer tissues and cell lines, and miR-4458 suppressed the proliferation and motility of breast cancer cells via CPSF4." (PMID 34013042, 2021). "Based on these findings, we hypothesized that NANOS1, PUM2, and CPSF4 may also serve as metastasis modifiers in breast cancer cells." (PMID 38410477, 2024). "Based on these findings, we hypothesized that the direct regulation of the Smarcd1 transcript by NANOS1, PUM2, and CPSF4 may be necessary for the metastasis of breast cancer cells." (PMID 38410477, 2024).
influenza (4 papers, 2018 to 2024). An acute viral infection of the respiratory tract, occurring in isolated cases, in epidemics, or in pandemics; it is caused by serologically different strains of viruses (influenzaviruses) designated A, B, and C, has a 3-day incubation period, and usually lasts for 3 to 10 days. "Additionally, inhibition of CPSF4 PAS recognition upon influenza infection by the NS1 protein causes RNA Polymerase II readthrough that leads to widespread changes in genome architecture dependent on NS1." (PMID 38191171, 2024).
prostate carcinoma (3 papers, 2023 to 2025). A carcinoma that arises from epithelial cells of the prostate gland. "Overall, these results revealed higher CPSF4 expression in PCa tissue, and further highlight the need for the exploration into the possible diagnostic and prognostic implications of CPSF4 in prostate cancer." (PMID 37629142, 2023). "Pathological analysis also revealed CPSF4 expression to be significantly higher in incidental and castrate resistant prostate cancer stages relative to benign prostate tissue." (PMID 37629142, 2023). "Our study’s first objective was to investigate the expression of the CPSF4 protein in our unique TMAs cohort; this group was comprised of patients diagnosed with various prostate cancer stages, such as incidental, advanced, and castrate-resistant PCa (CRPCa)." (PMID 37629142, 2023). "RNAseq data analysis from TCGA-PRAD database confirmed that high CPSF4 expression was not a feature specific to prostate cancer, but instead was a common characteristic of the 22 cancer subtypes analyzed within this study." (PMID 37629142, 2023).
colorectal cancer (2 papers, 2022). A primary or metastatic malignant neoplasm that affects the colon or rectum. "CPSF4 is upregulated in colorectal cancer tissues, and its knockdown inhibits the proliferation, migration, invasion, and stemness maintenance of colorectal cancer cells in vitro." (PMID 36349192, 2022).
hepatocellular carcinoma (2 papers, 2021 to 2023). A malignant tumor that arises from hepatocytes. "Seven key AS molecules related to CPSF4 were pointed out, and these molecules were not only related to the prognosis of hepatocellular carcinoma, but also related to expression of immune checkpoint genes and immune cell invasion." (PMID 37542549, 2023).
lung adenocarcinoma (2 papers, 2013 to 2015). A carcinoma that arises from the lung and is characterized by the presence of malignant glandular epithelial cells. "In this study, we investigated the expression and clinical significance of CPSF4 in lung adenocarcinoma and explored its roles and underlying mechanisms for cancer cell survival and proliferation." (PMID 24358221, 2013). "Association of CPSF4 expression with patient’s clinicopathological features in human lung adenocarcinoma." (PMID 24358221, 2013). "In this study, we showed that CPSF4 was highly expressed in lung adenocarcinomas cell lines and tumor tissues by comparison with normal lung cell and noncancerous lung tissues, respectively." (PMID 24358221, 2013). "Multivariate survival analyses revealed that higher CPSF4 expression was an independent prognostic factor for overall survival of the patients with lung adenocarcinomas." (PMID 24358221, 2013). "We have shown that CPSF4 is overexpressed in a subset of lung adenocarcinomas, which correlates with poor overall survival." (PMID 24358221, 2013). "Multivariate analysis showed that CPSF4 high expression is an independent prognostic factor for overall survival of lung adenocarcinomas patients." (PMID 24358221, 2013). "Knockdown of CPSF4 expression by siRNA significantly inhibited cell growth and induced apoptosis in lung adenocarcinoma cell lines through simultaneous inactivation of the PI3K/AKT and MAPK signaling and activation of the caspase-dependent apoptotic pathways." (PMID 24358221, 2013). "Multivariate analysis further indicated that high CPSF4 level and pN stage were independent prognostic factors for overall survival of patients with lung adenocarcinomas." (PMID 24358221, 2013). "We also found that CPSF4 overexpression was correlated with poor overall survival in patients with lung adenocarcinomas (P<0.001)." (PMID 24358221, 2013). "We also detected the expression of CPSF4 protein in lung adenocarcinomas tissue and 8 normal human tissues (heart, lung, liver, kidney, brain, spleen, ovary, and testis) by immunohistochemistry assay." (PMID 24358221, 2013). "Survival analyses showed that high expression of CPSF4 significantly correlated with shorter overall survival time in patients with lung adenocarcinomas (P<0.001, log-rank test)." (PMID 24358221, 2013). "In this report, we provide clinical evidence that CPSF4 overexpression predicts poor prognosis in lung adenocarcinoma patients." (PMID 24358221, 2013). "To investigate the clinicopathologic significance of CPSF4 in lung adenocarcinomas, we carried out immunohistochemical staining on a tissue microarray." (PMID 24358221, 2013). "We first examined the expression of CPSF4 protein in lung adenocarcinomas cell lines by Western blotting." (PMID 24358221, 2013). "We found that CPSF4 was highly expressed in lung adenocarcinoma cell lines and tumor tissue but was undetectable in 8 normal human tissues." (PMID 24358221, 2013). "The results from our in vitro experiments suggested that CPSF4 exerted its oncogenic function by regulating the proliferation and apoptosis of lung adenocarcinoma cells." (PMID 24358221, 2013). "The lung adenocarcinomas cell lines expressed the high levels of CPSF4 proteins as compared with the HBE." (PMID 24358221, 2013). "Moreover, clinicopathologic data from our tissue microarray showed that lung adenocarcinomas patients with highly expressed CPSF4 have shorter survival periods than those with CPSF4 low expression." (PMID 24358221, 2013). "Our results indicate that CPSF4 may be a potential prognostic biomarker and therapeutic target for lung adenocarcinoma." (PMID 24358221, 2013).
colon cancer (1 paper, 2019). "Moreover, ectopic overexpression of CPSF4 enhanced tumour growth in mouse models with colon cancer xenografts." (PMID 31546890, 2019).
liver cancer (1 paper, 2023). An epithelial or non-epithelial malignant neoplasm that arises from the liver. "More research is still required to determine whether CPSF4 can serve as a diagnostic marker or therapeutic target for liver cancer." (PMID 37542549, 2023). "It is necessary to further explore the regulatory role of CPSF4 on AS gene and its role in malignant phenotype, prognosis, and tumor microenvironment of liver cancer." (PMID 37542549, 2023). "They include the involvement of CPSF4 and related AS molecules in the onset and progression of liver cancer." (PMID 37542549, 2023). "As a result of our research, seven CPSF4-related AS genes were shown to be predictive of the prognosis for patients with liver cancer." (PMID 37542549, 2023). "In addition to offering useful indicators and novel prognostic treatment targets, our findings will contribute to understanding the regulatory role of CPSF4 in AS events in liver cancer and the function of AS genes in malignancies." (PMID 37542549, 2023). "However, previous studies on CPSF4 in liver cancer were limited to its polyadenylation mechanism." (PMID 37542549, 2023). "However, it is yet unknown how CPSF4 affects the onset and progression of liver cancer as well as the molecular system that controls it." (PMID 37542549, 2023).
prostate adenocarcinoma (1 paper, 2023). "Using the ‘The Cancer Genome Atlas’ Prostate Adenocarcinoma (TCGA PRAD) database, significant correlations were found between high CPSF4 expression and high-risk genomic abnormalities such as ERG-fusion, ETV1-fusion, and SPOP mutations." (PMID 37629142, 2023).
cancer (9 papers, 2009 to 2025). A tumor composed of atypical neoplastic, often pleomorphic cells that invade other tissues. "Potential oncogene cleavage and polyadenylation specific factor 4 (CPSF4) has been linked to several cancer types." (PMID 37629142, 2023). "Previous research has shown that CPSF4 is overexpressed in a number of cancer types and is related to prognosis." (PMID 37542549, 2023). "All 22 cancer types had a significantly increased expression of CPSF4 mRNA, according to the Pan-Cancer data analysis." (PMID 37629142, 2023). "Further studies are needed to document the mechanisms underpinning CPSF4 effects on the proliferation pathways in PCa and other forms of cancer." (PMID 37629142, 2023). "Understanding the function of CPSF4 in the process of metastasis is a crucial aspect of the progression of cancer." (PMID 37629142, 2023). "Then, through the signaling transmission of cascade proteins DNAH14 and CPSF4, it could enter the nucleus to downregulate TF MED17, resulting in an androgen-dependent reduction of cancer cells." (PMID 35164166, 2022).
tumor (9 papers, 2013 to 2024). "Furthermore, our findings along with those in the field implicate CPSF4 involved as being a crucial regulator of cell cycle progression and its association with both crucial tumor suppressors and oncogenes implicates it as a potential multilevel regulator of the proliferation process." (PMID 37629142, 2023). "It has been proposed that these mRNA 3′ ends maturation factors including CPSF4 maybe link to tumor suppression." (PMID 24358221, 2013). "A crucial component of AS is cleavage and polyadenylation-specific factor 4 (CPSF4), a component of the CPSF complex, but it is unclear how CPSF4-related AS molecules describe immune cell infiltration in the total tumor microenvironment (TME)." (PMID 37542549, 2023). "This study established a seven-gene profile (FGG, C3, FGA, JUN, CST3, CPSF4, and HIST1H2BH) prognostic stratification system demonstrated in LUSC based on Tumor Progression, Immune Infiltration, and Stem Index." (PMID 37841237, 2023). "In both 6DT1 and 4T1 cell lines, KD of NANOS1, PUM2, and CPSF4 did not consistently affect primary tumor growth but did significantly reduce the number of metastatic nodules on the lungs compared to shScramble control (shScr)." (PMID 38410477, 2024). "Particularly in PCa, it was documented that the expression of CPSF4 was significantly higher in tumor tissue as compared to normal tissue." (PMID 37629142, 2023). "Although the function of CPSF4 has been examined in different model systems, its potential role in tumors has not been fully investigated due to a lack of data regarding CPSF4 expression and tumor cell growth." (PMID 24358221, 2013).
CPSF4 also shares sentences with these, for which no sentence is quoted: infection (8 papers); viral infection (5); Autoimmunity (1); epidermolysis bullosa simplex (1); head and neck squamous cell carcinoma (1); leukemia (1); lymph node metastasis (1); muscular dystrophy (1); myocardial infarction (1); nemaline myopathy (1); ovarian carcinoma (1); stomach cancers (1); triple-negative breast carcinoma (1).